SNORA5C (small nucleolar RNA, H/ACA box 5C)
Synonyms: ACA5c
Gene: Small nucleolar RNA gene on chromosome 7 (45,104,906 to 45,105,042, reverse strand). Ensembl gene ENSG00000201772.
Gene Ontology:
Biological process: RNA processing
Cellular component: nucleolus
Homologues: Orthologues: chimpanzee SNORA5C (99% identical), macaque SNORA5C (96% identical), pig SNORA5C (82% identical), rabbit SNORA5C (82% identical), mouse Snora5c (80% identical), rat Snora5c (79% identical), guinea pig SNORA5C (72% identical). Paralogues in human: SNORA5A (66% identical), SNORA5B (61% identical).